PRMT5 (protein arginine methyltransferase 5)
Diseases named in the same sentence as PRMT5 in open-access papers (continued):
Sharing a sentence is not in itself a finding about the gene and the disease.
neurodegenerative disease (2 papers, 2018 to 2021). A disorder of the central nervous system characterized by gradual and progressive loss of neural tissue and neurologic function. "This research gap certainly warrants future clarification of the overall role of PRMT5 in human neurodegenerative diseases." (PMID 34685445, 2021). "The role of PRMT5 in neurodegenerative diseases is not well studied." (PMID 34685445, 2021).
connective tissue diseases (1 paper, 2025). "In this study, we determined association of anti-PRMT5 antibodies with two connective tissue diseases, SSc and RA." (PMID 40790333, 2025).
intestinal diseases (1 paper, 2023). "Together, these findings uncover PRMT5 as a novel regulator of mucosal defense and a potential therapeutic target for treating intestinal diseases." (PMID 37666668, 2023).
kidney diseases (1 paper, 2022). "Key lysine and arginine methyltransferases under investigation for renal disease treatment include EZH2, G9a, DOT1L, PRMT1 and PRMT5." (PMID 35559246, 2022). "However, PRMT5 has not been put into clinical trials for the treatment of kidney diseases, which requires exploration and support of various experimental theories." (PMID 35559246, 2022).
muscular disorders (1 paper, 2023). "Dysregulation of arginine methylations has been linked to pathomechanisms of several diseases, including neurodegeneration (i.e., PRMT1-ALS, PRMT5-PD), and muscular disorders." (PMID 37773136, 2023).
PRMT5 also shares sentences with these, for which no sentence is quoted: T-cell leukemia (3 papers); chronic myelogenous leukemia (2); colorectal adenocarcinoma (2); Crohn disease (2); Primary Sjogren's Syndrome (2); systemic lupus erythematosus (2); acute graft versus host disease (1); adult T cell leukemia (1); Alzheimer disease (1); bladder tumor (1); breast adenocarcinoma (1); Cachexia (1); choroidal neovascularization (1); CNS lymphoma (1); congenital generalized lipodystrophy type 2 (1); coronary artery stenosis (1); coronary atherosclerosis (1); diffuse midline glioma (1); DNA Repair Deficiency (1); endometrioid adenocarcinoma (1); endothelial dysfunction (1); epithelioid sarcoma (1); erectile dysfunction (1); esophageal squamous cell carcinoma (1); esophageal tumors (1); Eμ (1); follicular lymphoma (1); gallbladder adenocarcinoma (1); Granuloma (1); HIV-1 infection (1).
A further 32 diseases each share a sentence with PRMT5 in 1 paper.